FOXP3 (forkhead box P3)
Diseases named in the same sentence as FOXP3 in open-access papers (continued):
Sharing a sentence is not in itself a finding about the gene and the disease.
tumor (continued). "The potential regulatory roles of FOXP3 were dissected by an integrated approach, combining biochemical assays, analysis of patient survival, genetic manipulation of HCC cell lines, mouse xenograft tumor models and chromatin immunoprecipitation (ChIP) sequencing." (PMID 28903735, 2017). "Moreover, the dual role of FOXP3, participating in Treg cell development and function from one side and acting as a tumor modulator gene from other side should not be ignored." (PMID 28713192, 2017). "However, this radiation-associated fibrosis did not prevent the infiltration of Tim-3+ and Foxp3+ lymphocytes in the tumour microenvironment." (PMID 28871094, 2017). "Foxp3+ Tregs is a highly immunosuppressive subset of CD4+ T cells that is critical in s uppressing proliferation and cytokine production of other T cells, inhibiting tumor-specific immune responses and maintaining peripheral immune tolerance in cancer patients." (PMID 27974689, 2017). "By contrast, both CD4 and FoxP3 staining were primarily restricted to the stromal regions of tumor sections taken from patients with CRC regardless of whether they received enadenotucirev by IT injection or IV infusion." (PMID 28923104, 2017). "Although the percentage of CD25+FoxP3+ regulatory T cells among CD4+ T cells in the spleen of Her2/CT26 tumor-bearing mice was not changed significantly by the administration of TSA, TSA treatment significantly reduced the number of CD25+FoxP3+ Treg cells compared to vehicle treatment." (PMID 28489607, 2017). "Additionally, in tumor microenvironment macrophages (Mac), DCs, and MDSC suboptimally activate T cells which possibly plays significant roles in sustaining the phenotype of FoxP3+ T cells and Th17 cells in tumors." (PMID 29450136, 2017). "Furthermore, HDAC inhibition decreases Foxp3 expression in CD4+ T cells, which may increase an anti-tumor immune response by down-regulating suppressive Treg activity." (PMID 29371976, 2017). "However, FOXP3 expression is not restricted to Tregs as different tumor cells, including CMM cells, express the protein, and also to some extent CD8+ T-cells." (PMID 28851300, 2017). "Since FOXP3-CNS1 region is crucial for TGFβ-mediated FOXP3 induction, we next asked the question whether in tumor-CD8+ Treg cells SMAD3 regulates CNS1 activity or not." (PMID 28487507, 2017). "All these information tempted us to check whether RUNX3 has any role in the transcriptional activation of FOXP3 in tumor-induced CD8+ Treg cells or not." (PMID 28487507, 2017). "In contrast to HIF-1α-deficient tumor-infiltrating CD8+ T cells, however, PD-1 expression in VEGF-deficient tumor-infiltrating lymphocytes (TILs) is unaffected and there are no changes in FOXP3 expression levels in infiltrating CD4+ T cells." (PMID 29136509, 2017). "However, there was no significant relation between Foxp3 expression and the other clinical parameters, including age, tumor size, and histological type (all P > 0.05)." (PMID 28923073, 2017). "Researches have demonstrated that CD4+ CD25+ Foxp3+ Tregs inhibited proliferation, activation, degranulation, and production of granzyme A, granzyme B, and perforin of CD8+ T cells induced by anti-CD3/CD28 antibodies and are potent suppressors of autologous tumor-specific T cell responses." (PMID 28399886, 2017). "While IL-17AnegFoxp3neg and IL-17AnegFoxp3+ Treg cells do not affect tumour progression when compared with control tumour-bearing mice, both subsets of IL-17A-producing Foxp3+ and Foxp3neg cells enhance tumour progression compared with IL-17AnegFoxp3+ Treg cells." (PMID 28290453, 2017). "Tumor heterogeneity and stronger positive TIL associations were found in the non-relapse group, where both CD3–CD8 and FoxP3-Ki67 inter-correlations were found to be significant at the center of the tumor, while the correlation between C3FR and C8FR was significant at the invasive edge." (PMID 28885584, 2017). "Furthermore, the ratios of CD8+T:Foxp3 and CD8+T:PD-L1 were suppressed in tumor tissues." (PMID 29025424, 2017).
tumor (continued). "Moreover, a marked reduction in vascular endothelial growth factor (VEGF) expression, CD31+ blood vessels, CD4+ Foxp3+ Treg cells and the expression of MMP-2, MMP-9, MMP-13 and C-X-C motif chemokine receptor 4 (CXCR4) in the tumour stroma were observed in the Smad3−/− tumour microenvironment." (PMID 28262747, 2017). "The presence of Tr1 cells could indicate that Foxp3+ Treg cells are not the only cell type restricting eBL tumor response, which has implications for future Treg-modulating therapy in eBL." (PMID 28033393, 2016). "Furthermore, RSV-treated tBregs adoptively transferred into 4 T1 tumor-bearing mice lacked the ability to expand FoxP3+ Tregs in vivo and promote lung metastasis as compared to mock-treated tBregs." (PMID 27437104, 2016). "Additionally, Th17 cells may also exert immunosuppressive functions via direct inhibition of tumor-specific CD8+ T effector cells, and development of IL-17+Foxp3+ regulatory T cells." (PMID 27341128, 2016). "Moreover, in a recent study, multispectral imaging of CD3, CD8, FOXP3, CD163, and PD-L1 was used to analyze the tumor microenvironment as a predictor of the successful generation and expansion of autologous tumor-reactive tumor infiltrating lymphocytes (TIL) in melanoma patients." (PMID 26885371, 2016). "It has been shown that CD25+Foxp3+ Tregs led to increased numbers of LN-resident DCs but neither the impact of the Treg depletion on the different DC subsets nor the cell-mediated response to tumour cells have not been examined in details." (PMID 27341421, 2016). "Similarly to the total score, FOXP3 and PD-L1 expression in the different tumor compartments failed to predict for the clinical outcome in our analysis." (PMID 27329602, 2016). "In addition, vaccine did not significantly alter levels of tumor-infiltrating CD25 + Foxp3+ regulatory CD4+ T-cells (Data not shown)." (PMID 28018602, 2016). "On the other hand, type 2 CD4+ T-helper cells (Th2), including Forkhead box P3 (FOXP3) CD4+ regulatory T-cells, inhibit CTL function, support proliferation of B-lymphocytes, and may promote an anti-inflammatory immune response that could enhance tumor growth." (PMID 27777769, 2016). "In contrast, αCD40 did not significantly change the number of tumour infiltrating FoxP3+ Treg." (PMID 26918344, 2016). "Further, the frequency of CD4+ T lymphocytes expressing the transcription factor FoxP3, a marker of regulatory T cells (Treg), did not significantly change in the tumor microenvironment or in the spleen, but modesty increased in the blood of tumor-bearing mice." (PMID 27936099, 2016). "Thus, the absence of LC3II correlated with intratumoral, but not peritumoral, infiltration of Foxp3+ Tregs, CD68+ tumor-associated macrophages and less CD8+ T cytotoxic lymphocytes." (PMID 27917371, 2016). "With Foxp3 as the marker, CD4+ helper T cells could be classified into effective T cells that are helpful to promote immune responses (CD3+CD4+Foxp3-), as well as regulatory T cells (Tregs) (CD3+CD4+Foxp3+) which could hamper effective anti-tumour immune responses." (PMID 27767031, 2016). "FOXP3 cells were present in 75% of tumor samples and absent in the remaining 25%." (PMID 27487262, 2016). "Neither Foxp3+ nor CD8+ TIL density alone had any correlation with tumor PD-L1 expression." (PMID 26317902, 2015). "Thus, the tumor microenvironment in Apc/Min+ mice have markedly increased numbers of Foxp3+ Tregs but only moderately increased IL-17A+ CD4 T cells in the LP, suggesting that Apc/Min+ Foxp3+ Tregs are altered in the LP." (PMID 26146642, 2015). "Since FOXP3 expression correlated to CD14 expression, the presence of macrophages or dendritic cells expressing CD14 may be responsible for the activation of effector T cells, which in turn limited tumor progression." (PMID 26161395, 2015).
tumor (continued). "Furthermore, the area occupied by CD45+ immune cells, Tbet+ cells but not Foxp3+ cells within the tumor were, in addition to the lymph node status of patients, associated with a longer disease free survival and disease specific survival." (PMID 26357849, 2015). "Moreover, FOXP3+T-cells added independent prognostic information for PDAC patients in a multivariate model including other established and independent prognostic factors such as tumor budding." (PMID 25669968, 2015). "In this tumour immunity microenvironment model, with E-cadherin + DC treatment carrying the CEA526-533 antigen peptide, the transcription of T-bet and RORγt was enhanced compared with mice that received E-cadherin- DCs and the PBS control mice, whereas FOXP3 transcription was reduced." (PMID 25651850, 2015). "Interestingly, their deficiency specifically suppresses PD-1 expression in CD8+ effector T cells without affecting CTLA-4 expression or the percentages of tumor-infiltrating CD4+Foxp3+ regulatory T cells (Tregs)." (PMID 25851535, 2015). "In addition, and opposed to murine models, there is evidence suggesting that FoxP3 can be also expressed in cells without regulatory function, such as epithelial and tumor cells." (PMID 26529008, 2015). "While we did not directly compare the variation in staining of different FOXP3 antibodies in this study, these prior studies indicate that the 236A/E7 clone (Ab20034) is the most suitable antibody for IHC detection of human FOXP3 in both tumor and Treg cells." (PMID 24406338, 2014). "Furthermore, we did not detect any Foxp3 expression in other myeloid cells (F4/80−/CD11b+ cells) or in dendritic cells (DCs) or B cells from organs in naïve or IK tumor-bearing mice." (PMID 25264896, 2014). "Therefore, using Foxp3 as the sole marker of Tregs may lead to discordant conclusions, and multistaining FCM assays might provide more accurate Treg frequency in tumor tissues than IHC-based methodology." (PMID 24637664, 2014). "However, there was no significant change in the CD4+CD25+FoxP3+ tumor cell population in the local pGmCSF-b7.1 treatment." (PMID 25034887, 2014). "Distinct differences were observed in Foxp3(+) regulatory T (Treg) cells and CD56(+) natural killer (NK) cells; a higher density of Foxp3(+) Treg cells was found in metastatic lymph nodes and more infiltration of CD56(+) NK cells in tumor regressed lymph nodes." (PMID 24885770, 2014). "Also, we were able detect a very faint band for Foxp3 mRNA in some macrophage cells sorted from BM from IK-tumor bearing mice but not naïve mice confirming our previous FACS analysis." (PMID 25264896, 2014). "Exploring the interaction between CD4+CD25+Foxp3+Treg and CD4+IL-17+ Th17 cells has great implications for understanding regulation of the immune inflammatory microenvironment and for the clinical application of traditional Chinese medicine in the reversion of tumor growth and tumor immune escape." (PMID 24949077, 2014). "In addition, the migration of Foxp3-positive cells into the tumor tissues was not significantly correlated with the OS as well as DFS (data not shown), and thus the data obtained with Foxp3-staining are not shown in this report." (PMID 25461761, 2014). "Therefore, Tim-3, but not PD-1, marks the population of Foxp3+ T cells in the tumor microenvironment." (PMID 23526963, 2013). "Extrapolating from this, it is tempting to conclude that majority of tumor-Treg cells are likely nTregs based on their Foxp3 stability and not iTregs as Foxp3 unstable Treg cells would otherwise constitute a sizable fraction of tumor-Tregs if they were induced from conventional CD4+ T cells." (PMID 23874336, 2013). "Although this concept and process of cellular conversion and/or plasticity among CD4+FoxP3+ TReg cells remains controversial, it is clear that the biological properties of CD4 TReg cells and their subpopulations are heterogeneous and influenced by the tumor environment in which they infiltrate." (PMID 23533029, 2013).
tumor (continued). "However, this does not appear to be the case with IL-35, as tumor-infiltrating CD4+Foxp3+ nTregs had higher levels of suppression then infiltrating Foxp3− iTr35 cells." (PMID 24151492, 2013). "The characterization of TILs polarization in PDAC was initially reported in, in which the presence of Th2, Th1 and Tregs cells in tumor samples was evaluated by immunohistochemistry using specific antibodies for GATA-3 (i.e., to detect Th2 cells), T-bet (i.e., to detect Th1 cells) and FoxP3." (PMID 23950747, 2013). "In this report, authors concluded that since the TCR repertoires of either population were largely non-overlapping, the tumor-infiltrating Tregs are likely of natural origin as a significant overlap would have been observed if a fair amount of CD25− cell conversion to Foxp3+ cells occurred." (PMID 23874336, 2013). "Alternatively, the expression of inhibitory molecules on the surface of tumor cells could promote the expansion and accumulation of nonresponsive anergic T cells or CD4(+)CD25(+)Foxp3(+) T-regulatory cells (Tregs) within the tumor microenvironment." (PMID 23533456, 2013). "Interestingly, Tim-3+Foxp3+ CD4 T cells were preferentially distributed in the tumor nest, rather than the peritumoral stroma." (PMID 23526963, 2013). "Although both iTreg and nTreg in the tumor may be indistinguishable in terms of having an effector phenotype, assessing Foxp3 epigenetic modification patterns could be useful to differentiate nTregs from iTregs." (PMID 23874336, 2013). "It is extremely important however, to determine whether or not Foxp3+ Tregs are responsible, directly or indirectly, for driving the acquisition of suppressor functions of tumor-infiltrating Foxp3−CD4+ T cells." (PMID 23874342, 2013). "Tumor-challenged mice were treated and on day 5 post treatment, mice from each treatment group were sacrificed and the cells from the spleen and draining lymph node were stained, using direct immunofluorescence, for the presence of Tregs as defined by their co-expression of CD3, CD4 and Foxp3." (PMID 23840786, 2013). "Although it is not clear whether chemotherapy can be used to counter Foxp3+Treg-derived tumor protection, it would, however, seem to activate the immunocompetence needed for vaccine response." (PMID 23725550, 2013). "However, tumor burden and radiation therapy is accompanied by an increase in the number of T regulatory cells (Treg) in the spleen, as measured by CD4+ cells expressing CD25 and FoxP3." (PMID 23936036, 2013). "In addition, there was a strong positive correlation between CD3+, CD8+ and FoxP3+ TIL densities observed in both the tumor center and the invasion front, regardless of the compartment (p<0.01, data not shown)." (PMID 23613769, 2013). "However, multivariate analysis demonstrated that FOXP3 expression in TILs, unlike that in tumor cells, was an independent prognostic factor for OS (Table IVB)." (PMID 24649219, 2013). "In addition, depletion of peripheral CD25+Foxp3+ Tregs in tumor-bearing mice did not enhance the tumor-inhibitory effect of FTS." (PMID 22323550, 2012). "Higher percentages of CD4/Foxp3 positive cells were found in spleens and LN from nontumor-bearing Pmel/Foxp3EGFP mice compared to C57BL/6 Foxp3EGFP mice (overall average 25% compared with 12%), but there was no additional Foxp3 enrichment among CD4 TIL in tumor-bearing animals." (PMID 22112546, 2011). "Thus, CD8 and CD4 transgenic T cells in these animal models failed to undergo peripheral induction of Foxp3 in a tumor microenvironment." (PMID 22112546, 2011). "In their study, tumor-infiltrating FOXP3+ Tregs are much rarer in non-upper aerodigestive tract (UAT)-NKTCLs than in UAT-NKTCLs and in patients with poor performance status (PS), which might lead to poor clinical outcome of patients with decreased Tregs." (PMID 22151904, 2011). "Although ATLL cells may exert immune suppressive effects, ATLL is not necessarily a tumor of classical FOXP3+ Tregs." (PMID 22151904, 2011).
tumor (continued). "However, in neither TCR transgenic mouse did we find evidence of Foxp3 induction among tumor-infiltrating lymphocytes (TIL), splenocytes (SPL) nor lymph nodes (LN)." (PMID 22112546, 2011). "This suggests that the levels of FOXP3 expression, as for SPARC, in the patient's primary tumour may play an important prognostic role that could assist in distinguishing between stage II cancers that would, and would not, benefit from post-operative adjuvant chemotherapy." (PMID 21818290, 2011). "However, in contrast to the previously reported absence of Treg cells in tumour epithelium, intraepithelial FOXP3-positive cells, although sparse in some tumours, were detected in all but one of the analysed lesions." (PMID 18985040, 2008). "Recent reports suggested that thymic-derived CD4+CD25+ regulatory T cells (Treg; Foxp3+ lymphocytes) participate in the control of tumour immunity, but whether Treg control tumour immunity in OSCC has not been established." (PMID 18349839, 2008). "However, inhibition of ZDHHC2, ZDHHC3, and ZDHHC7, which are responsible for palmitoylating Foxp3, might reduce the nuclear localization and stability of Foxp3 in both peripheral lymphoid tissues (e.g., spleen, lymph nodes) and tumor-infiltrating Tregs." (PMID 40814339, 2025). "Gene expression levels of FoxP3, CTLA4, and GITR were significantly higher in both unstimulated and PHA-stimulated PBMCs from BC patients compared to healthy controls, indicating heightened Treg cell activity that may contribute to tumor progression by suppressing anti-tumor immune responses." (PMID 40281554, 2025). "In conclusion, PD-L1 and FOXP3 are noticeably present in the immune environment of pre-malignant lesions of the anal canal, penis, and vulva induced by HR-HPV, similar to that described in cervical neoplasia and in other non-viral-associated pre-invasive neoplasms of other organs." (PMID 40270290, 2025). "This FOXP3-miR-155 axis, although not directly correlated in our cohort, may still be active at the cellular level, contributing to the delicate balance between immune tolerance and immunosuppression in the tumor microenvironment." (PMID 40806346, 2025). "Based on these findings, the tumor growth suppression observed in B16F10-mock tumors during CD4+ T cell depletion experiments may be primarily attributed to the removal of suppressive CD4+ T cells, including Foxp3+CD25+ Tregs, which may have enhanced CD8+ T cell-mediated anti-tumor immunity." (PMID 40243581, 2025). "Furthermore, we did not differentiate the expression of FOXP3 between tumor cells and immune cells." (PMID 40587482, 2025). "We speculate that CD25+ or CD25+FOXP3+CD45RA− stromal cell count reflects the stromal responses to antitumoral immunity, and that their ratios to CD8+ cell count may be equivalent to the strength of antitumoral immune status particularly involved in tumor chemosensitivity." (PMID 39232704, 2024). "In the present study, we did not investigate whether the CD4/CD8 TIL and FOXP3 levels in the tumor specimens correlated with VEGFR2 expression, and the biological mechanism underlying the increased efficacy of RD after continuous ICI treatment for >180 days remains unresolved." (PMID 38013668, 2024). "Additionally, the tumor sample contained various other cell types, including epithelial cells (EPCAM+), pStr (MKI67+) CD4+T cells (CD4+), CD8+ T cells (CD8A+), macrophages (CD68+), and regulatory T cells (FOXP3+), which were further validated by our single-cell data." (PMID 39676856, 2024). "Additionally, FOXP3 is not exclusive to Tregs, as some non-regulatory T cells and even tumor cells may also express this marker." (PMID 39877377, 2024). "In addition, there were no changes in FOXP3 mRNA expression or in the numbers of Tregs in draining lymph nodes and in spleens of tumor bearing mice, confirming that intratumoral Treg had enhanced sensitivity to ASO FOXP3 in vivo compared to other Treg populations." (PMID 39234236, 2024).